GREM1 (gremlin 1, DAN family BMP antagonist)
Diseases named in the same sentence as GREM1 in open-access papers (continued):
Sharing a sentence is not in itself a finding about the gene and the disease.
cancer (continued). "Again, most published research suggests that high levels of GREM1 represent a cellular mechanism by which CSCs can maintain their pluripotency, which presents a barrier to chemotherapy treatments aimed at the destruction of cancer cells." (PMID 40277903, 2025). "GREM1 is secreted by both cancer cells and stromal cells within the tumor microenvironment." (PMID 40277903, 2025). "To further clarify GREM1’s role in cancer prognosis, we performed a pan-cancer analysis in the TCGA cohort, showing that high GREM1 expression is strongly associated with poor prognosis across multiple cancer types, especially in tumors with high TMB and substantial immune cell infiltration." (PMID 40066442, 2025). "Targeting this pathway by inhibiting GREM1 using neutralizing antibodies or small molecules may hold early-stage promise for novel therapeutic strategies aimed at reducing CSC burden in cancers and improving patient outcomes." (PMID 40277903, 2025). "High GREM1 expression frequently correlates with lower survival rates, indicating it may serve as a key driver gene or regulatory factor in these cancers." (PMID 40066442, 2025). "The GREM1Mut, which we clearly demonstrated, does not bind to BMP2 in both HCT116 and C2C12 cells may be a valuable reagent to further refine our understanding of GREM1-RTK signaling in cancer and other diseases." (PMID 41033552, 2025). "Interestingly, GREM1 is overexpressed in various carcinomas, such as those of the colon, lung, stomach, liver, and breast, influencing cancer cell proliferation, migration, and invasion." (PMID 40069570, 2025). "The exact mechanisms driving GREM1 overexpression in cancer cells are not fully understood." (PMID 40277903, 2025). "Regulation of CSC biology may also represent an important role for GREM1 in modulating human cancer." (PMID 40277903, 2025). "Notably, elevated GREM1 expression has been observed in fibroblasts across various carcinomas, where it contributes to tumour cell proliferation and invasion." (PMID 41281745, 2025). "For example, higher levels of GREM1 were suggested to promote cancer stem cell (CSC) maintenance." (PMID 37615860, 2023). "GREM1 can inhibit tumor cell proliferation, migration, and invasion in various cancers." (PMID 36895470, 2023). "Kapoor and colleagues identified that a Grem1 + fibroblast reticular cells in the stroma maintained dendritic cell homeostasis in lymphoid tissue, which may play an important role in some cancers." (PMID 37615860, 2023). "Varieties of public databases and online software were employed to analyze the expressions at transcription and protein levels of GREM1 in multiple malignant neoplasms including PDAC, and in addition, its potential pro-tumoral functions in PDAC were further evaluated." (PMID 36091126, 2022). "The effect of GREM1 on the prognosis of malignant tumors remains elusive." (PMID 35883579, 2022). "We initially analyzed the mRNA expression of GREM1 in human cancers using the database GEPIA." (PMID 36091126, 2022). "Recently, numerous studies have reported the oncogenic role of GREM1 in cancer." (PMID 33287358, 2020). "Since EMT is an important step in cancer metastasis, its induction by GREM1 may affect tumour progression." (PMID 32572171, 2020). "However, GREM1 has been reported to function independently of BMPs in the proliferation, migration, and invasion of cancer cells." (PMID 33287358, 2020). "Interestingly, visual inspection indicated that fibroblasts expressing GREM1 clustered around nests of cancer cells, suggesting a potential juxtacrine interaction between these cell types mediated by this pathway." (PMID 32381040, 2020). "Since BMPs have dual functions in cancer, whether the mechanism by which GREM1 promotes cancer is related to BMPs remains unclear." (PMID 33287358, 2020). "Thus, overexpression of GREM1 in cancer cells is likely to accelerate their growth and metastasis by activating distinct oncogenic pathways." (PMID 32572171, 2020).
cancer (continued). "Although many studies have reported the tumor promoting function of GREM1, mechanisms involved in the overexpression of GREM1 and mechanisms by which GREM1 is involved in the growth of cancer cells remain unclear." (PMID 33287358, 2020). "Interestingly, it has been suggested that GREM1 can induce cancer cell motility in the cancer invasion front which indicates the site where cancer metastasis occurs." (PMID 33287358, 2020). "We and others have previously highlighted the association between CMS4, high levels of cancer-associated fibroblasts (CAFs), and poor prognosis in CRC Therefore, we next set out to delineate the cellular-specific source of GREM1 from within the TME of stromal-rich CMS4 tumours." (PMID 31384391, 2019). "We identified TGFβ secreted by cancer cells as a strong driver of GREM1 expression by CAFs." (PMID 31533776, 2019). "We found that GREM1 expression in CAFs is particularly high in close vicinity of cancer cells." (PMID 31533776, 2019). "In addition, in non-cancer tissue we find that GREM1 mRNA is higher in smooth muscle cells compared to any other cellular lineage or tissue." (PMID 31384391, 2019). "However, the effects of Grem1 on CAFs’ function and on the interaction between (breast) cancer cells and fibroblasts are unclear." (PMID 31533776, 2019). "In contrast, Gremlin1 (GREM1) showed various degree of upregulation in cancer lesions." (PMID 29720137, 2018). "Aberrant epithelial expression of GREM1 has been documented in diverse carcinomas." (PMID 28977865, 2017). "Given the demonstrated role of GREM1 in imposing a stem cell phenotype on cells outside the crypt base, it seems plausible that the poor treatment response may be secondary to an effect of GREM1 on cancer stem cell plasticity." (PMID 25974319, 2015). "SPP1, CTHRC1 and GREM1 are candidate biomarkers to identify the cancer." (PMID 24299561, 2013). "Additionally, we found that GREM1 expression was significantly upregulated following irradiation (p = 0.031; Wilcoxon signed rank test) or replicative exhaustion (p = 0.021; Wilcoxon signed rank test) in MSCs from young non-cancer controls." (PMID 40263435, 2025). "Thus, GREM1 expression may play a role in both the “seed and soil” in a range of cancers, affecting the tumor stroma and the CSCs, creating a tumor-permissive environment for both primary tumors and metastases." (PMID 40277903, 2025). "Importantly, treatment with an anti-Grem1 antibody abrogated this pro-cancer polyposis phenotype." (PMID 41033552, 2025). "Similarly, GREM1 can also promote invasion of cancer cells by activating the EGFR pathway." (PMID 37333824, 2023). "However, GREM1-mediated responses that occur in other cells than CAFs, such as endothelial cells in the tumor stroma may also be significant for cancer development." (PMID 37615860, 2023). "Additionally, GREM1 has been reported to be both tumor promotive and suppressive in cancer." (PMID 33967807, 2021). "As such, overexpression of GREM1 can increase the activity of intracellular kinases or transcription factors that might regulate a variety of pathological conditions, particularly affecting the growth, migration, and metastasis of cancer cells." (PMID 33287358, 2020). "Thus, the profibrogenic ability of Grem1 could contribute to its role in promoting cancer cell invasion mediated by activated fibroblasts and CAFs." (PMID 31533776, 2019). "Moreover, these GREM1-expressing CAFs were also observed in many other carcinomas." (PMID 28346486, 2017). "Results indicate that GREM1 is highly expressed in LUAD and is overexpressed in other cancers such as BRCA, HNSC, KIRC, KIRP, THCA, and UCEC." (PMID 40066442, 2025). "Previous studies indicate that GREM1 modulates TME by inhibiting BMP signaling, altering cancer cell growth, differentiation, and stromal-immune interactions, thereby driving tumor progression and metastasis." (PMID 40066442, 2025).
cancer (continued). "The role of GREM1 in human cancer is well detailed, with most of the research supporting a tumor promoter role for GREM1 overexpression in CRC and other human cancers." (PMID 40277903, 2025). "GREM1 drives chemoresistance by antagonizing bone morphogenetic protein (BMP) signaling, thereby sustaining cancer stemness and suppressing apoptotic pathways." (PMID 41048340, 2025). "Our transcriptomic analyses of CM-treated HOSEs uncovered gene-expression profiles defining responses to cancer-like TME, highlighted by STAT1, ISG15, and OAS1 in HOSE1C and ITGA2, GREM1, and CDH13 in HOSE2C." (PMID 39634630, 2024). "The presence of WNT5A+ inflammatory fibroblasts was confirmed by the overlapping signals from the WNT5A, GREM1, and PDGFRA RNA probes in the desmoplastic stroma of cancer tissues." (PMID 38744958, 2024). "Our results extend these implications to PDAC, highlighting the importance of the spatially correlated crosstalk between CTHRC1+GREM1+ myCAF and SPP1+APOE+ TAM that drive fibrosis, immunosuppression, and EMT in PDAC and potentially other cancers." (PMID 39075108, 2024). "Furthermore, secreted bone Morphogenetic protein antagonist, Gremlin1 (GREM1), can inhibit the osteogenic transformation of adipocytes, and some scholars believe that the expression of GREM1 can be a marker of activated myofibroblasts in cancer matrix or scar tissue." (PMID 37491214, 2023). "Other studies have also shown that PTGDS, GREM1, LAMA4, S100A14, PREX2, and GLS2 have potential value in promoting cancer progression and predicting cancer prognosis." (PMID 37306872, 2023). "In terms of mRNA expression, GREM1, IGF2, CTGF, and PLAU showed significant changes between cancer adjacent and cancer free polyps." (PMID 35486660, 2022). "FOXL1, in turn, directly up-regulates Grem1 expression to antagonize BMP signaling and promote cancer progression by suppressing differentiation of Lgr5+ stem cells while inducing epithelial proliferation." (PMID 33197448, 2021). "Using organoid culture and a preclinical mouse model, our data support that BMP signaling imbalance, regulated by Grem1 and Islr, drives CRC progression and is a key target for cancer treatment." (PMID 33197448, 2021). "Considering the possible plasticity of CAFs,2 it is plausible that Grem1+ CAFs and Islr+ CAFs could undergo phenotypic interconversion during tumor development, a state of dynamic flux between a relatively polarized cancer-retarding or cancer-promoting microenvironment." (PMID 33197448, 2021). "GREM1 was not only found to be upregulated by stromal cells isolated from BCC, but also for a number of other cancer types such as prostate, colon, pancreas and esophageal cancer." (PMID 32486027, 2020). "Thus, GREM1 secreted from CAFs may also promote the metastasis of cancer cells." (PMID 33287358, 2020). "As our results show, GREM1 can activate various intracellular signalling molecules such as ERK and Akt involved in cancer cell proliferation and survival." (PMID 32572171, 2020). "This enabled us to examine genes on an individual basis, and many genes important in the development of CRC, and cancer in general, were upregulated in the CAP tissues relative to the CFPs, including CXCL5, GREM1, IGF2, CTGF and PLAU." (PMID 29453410, 2018). "These merged DMxDE datasets suggest some known or previously reported/suspected cancer genes [PR: SPARCL1, NQO1, CST1, MELK1, DPT, FAM83A, MMP9; GB: FOXM1, TFAP2, GREM1, ITGA8, GRIA1, SLIT3] as well as many previously unreported genes/loci." (PMID 26683690, 2015). "GREM1, a BMP antagonist, has emerged as a key regulator of cancer development and progression." (PMID 40277903, 2025). "GREM1 was significantly upregulated in MSCs from older non-cancer controls compared with young non-cancer controls (p = 0.0003; Kruskal Wallis test with Dunn’s multiple comparisons post-test)." (PMID 40263435, 2025).
cancer (continued). "GREM1 (gremlin-1), a secreted BMP antagonist, promotes angiogenesis and pro-tumorigenic signaling pathways, and neutralizing antibody strategies have demonstrated efficacy in preclinical fibrosis and cancer models." (PMID 41198614, 2025). "Also, other active proteins such as Gremlin-1 (GREM1), bone morphogenetic protein 4 (BMP4), TGF-β, MT-MMPs, laminin-5, integrin, and EGFR promote cancer cell migration and invasion and EMT." (PMID 39120301, 2024). "Of note, several of these genes (such as Grem1, Hmga1, and Krt13) are specifically expressed by cancer cells, but not by other cell populations, indicating that these genes are potential markers associated with tumor metastasis." (PMID 37190324, 2023). "One of the first reports of a non-BMP binding partner for GREM1 in cancer cells was human tyrosine 3-monooxygenase/tryptophan 5-monooxygenase activation protein eta (14-3-3-eta, also called YWHAH." (PMID 37615860, 2023). "Notably, among the genes downregulated upon DSCAM-AS1 knockdown were several proliferation activators of endometrial (and other) cancer cells, like NOTCH1, HMGA2, PTK2/FAK, FOSL1, GREM1 and EGR1." (PMID 35885035, 2022). "Grem1 is also overexpressed in the desmoplastic invasion front of CRC, a zone where many cancer metastases are speculated to originate." (PMID 35815339, 2022). "By targeting the upstream determinants of mesenchymal expression, such as TGF-β and FOXL1 or by targeting the downstream drivers of BMP signaling such as GREM1 and ISLR, one may identify new approaches to prevent and treat cancer." (PMID 33197448, 2021). "Interestingly, GREM1+ CAFs were spatially distinct from ISLR+ CAFs in desmoplastic human CRC, with ISLR+ CAFs located in closer proximity to cancer cells than GREM1+ CAFs." (PMID 33197448, 2021). "Thus, as one of the target genes of ERRα, GREM1 can again activate the EGFR–ERRα axis and eventually functions as an enhancer or an amplifier for the expression of genes involved in cancer cell growth and proliferation." (PMID 32572171, 2020). "Moreover, by injecting ectopic Grem1-producing M2 and MDA-MB-231 cells into the DoC of zebrafish embryos, we found that Grem1 strongly promoted the extravasation of cancer cells." (PMID 31533776, 2019). "GREM1, a member of antagonist family that has been shown to relay the sonic hedgehog (SHH) signal from the polarizing region to the apical ectodermal ridge during limb bud outgrowth in mouse, is involved progression of various cancers." (PMID 31043858, 2019). "We identified variable amounts of GREM1 expressed in fibroblast-like cells, i.e., CAFs, whereas there were no detectable levels of GREM1 in cancer-adjacent normal tissues or adjacent cancer-free breast tissues." (PMID 31533776, 2019). "In several cancers, Grem1 reduces the negative effect of BMPs on stemness, proliferation, migration, and invasion of cancer cells." (PMID 31533776, 2019). "It remains an intriguing possibility that GREM1 signaling via VEGFR2 may represent a previously undiscovered mechanism by which GREM1 regulates CSC pluripotency and chemotherapy resistance in human cancers." (PMID 40277903, 2025). "In addition, we found that the BMP targets, ID1 and ID2, were significantly downregulated in the carcinomas, whereas GREM1 and NOG expression increased, albeit not significantly in the case of GREM1." (PMID 27492255, 2016). "Expression of GREM1 can regulate cancer cell growth positively or negatively." (PMID 23502471, 2013). "Although these studies were performed under conditions of injury rather than cancer, one could hypothesize that similar functions of Grem1+ fibroblasts/mesenchymal cells in a cancer setting create a favourable microenvironment in which tumor progression is enhanced by increasing stemness." (PMID 37615860, 2023). "However, it may be entirely possible that GREM1 expression in CAFs is merely a marker of activated fibroblasts seen in scar tissues rather than an active promoter of cancer progression." (PMID 28346486, 2017).
cancer (continued). "Therefore, understanding the role of GREM1 in cancer, particularly in modulating CAF behavior and their pro-tumoral properties, is important for elucidating the complexities of tumor-stroma interactions and could potentially offer avenues for targeted therapeutic interventions in cancer." (PMID 40069570, 2025). "Therefore, it is necessary to evaluate the function and mechanism of GREM1 by focusing on the molecular exchange between cells in terms of the tumor microenvironment rather than the correlation between GREM1 and BMP in cancer cells themselves." (PMID 33287358, 2020).